G6PD (glucose-6-phosphate dehydrogenase)
Diseases named in the same sentence as G6PD in open-access papers (continued):
Sharing a sentence is not in itself a finding about the gene and the disease.
G6PD deficiency (continued). "The genetic defect of GLUT1 or G6PD causes a spectrum of diseases, but the vast majority of persons with G6PD deficiency also may be asymptomatic." (PMID 37597521, 2023). "According to the WHO prequalification technical specifications, an in vitro diagnostic test for G6PD deficiency must be able to distinguish between normal, G6PD-deficient with enzyme level below 30%, and G6PD-intermediate with 30%–80% of normal enzymatic activity." (PMID 37388931, 2023). "Thus, abnormal G6PD activity is associated with numerous pathophysiological cellular alterations and diseases, including clinical G6PD deficiency (the most common blood disorder, with a prevalence of 1 in 20), infection, and cancer." (PMID 37798264, 2023). "There is potential for a device such as FINDER to assist in the implementation of the new American Academy of Pediatrics’s guidelines for G6PD testing in newborns with recurring high bilirubin concentrations, as well as testing for G6PD deficiency prior to rasburicase therapy." (PMID 38132231, 2023). "G6PD deficiency is an X-linked genetic disorder caused by mutations in the G6PD gene." (PMID 37967096, 2023). "These opposing effects could account for the global action of G6PD deficiency in animals and humans, explaining, for example, the fact that a moderate overexpression of G6PD is able to increase the median lifespan in animals." (PMID 36829893, 2023). "Immunoglobulins A and G levels were increased in G6PD patients and C4 complement decreased, suggesting a possible activation of the complement system in G6PD deficiency, presumably through the classical pathway and with the production of circulating immune complexes." (PMID 37753082, 2023). "Understanding G6PD treatment is crucial for its effective management, and this knowledge, particularly concerning fluid intake and blood transfusion, was found to be statistically significant in relation to having a child with G6PD deficiency." (PMID 38229803, 2023). "G6PD deficiency is caused by inherited mutations of the X-linked gene G6PD." (PMID 36949502, 2023). "From the findings whether females are protected by G6PD deficiency is uncertain due to variation in study design, G6PD and to genetic differences between populations." (PMID 38062464, 2023). "Recent studies have suggested that G6PD plays an important role in immune response and that G6PD deficiency may increase susceptibility to infections." (PMID 36905446, 2023). "Alteration in other genes encoding regulatory proteins involved in the regulation of G6PD expression might also contribute to G6PD deficiency by decreasing transcriptional level or affecting post-translational modification of the G6PD protein." (PMID 37967096, 2023). "Although genetic tests for the G6PD gene are important for the diagnosis of G6PD deficiency, G6PD enzyme tests to predict the pathogenicity of variants have become popular and are considered the best tests due to their potential to cause clinical manifestation." (PMID 37176619, 2023). "G6PD deficiency and intermediate G6PD were widely distributed across age groups." (PMID 37176619, 2023). "The availability of an FDA-cleared platform for rapid G6PD testing with low sample volumes could be critical to the screening success of newborns and pediatric patients for G6PD deficiency." (PMID 38132231, 2023). "This retrospective study aimed to examine the effect of COVID-19 on patients with G6PD deficiency by comparing the laboratory parameters of patients with G6PD enzyme deficiency alone, COVID-19 alone, and those with both COVID-19 and G6PD enzyme deficiency treated at a major Saudi tertiary center." (PMID 37376524, 2023). "If an increased viral load corresponds with increased infectivity, COVID-19 patients with G6PD deficiency could therefore be more contagious than patients with in-tact G6PD enzymes." (PMID 36905446, 2023).
G6PD deficiency (continued). "Patients with inherited G6PD deficiency may have insufficient total G6PD activity to prevent primaquine-induced hemolysis with older erythrocytes being the most susceptible due to a physiological reduction in antioxidant capacity with age." (PMID 36509054, 2023). "We previously performed these methods to evaluate the effect of mutation on the stability of the G6PD variants, which could be the most frequent deleterious effect caused by mutations and could explain the clinical manifestations of G6PD deficiency." (PMID 37628871, 2023). "In the current study, the average levels of awareness of G6PD deficiency were 37.8%, knowledge of G6PD risk factors was 34.5%, understanding of G6PD clinical presentation stood at 38.2%, knowledge about G6PD treatment reached 32.15%, and familiarity with sources of G6PD information was 17.4%." (PMID 38229803, 2023). "After adjusting for thalassemia and hemoglobinopathies commonly observed in this region, we found that G6PD deficiency, G6PD ViangchanG871A, female gender, neonatal anemia (Hb < 15 g/dL), ABO incompatibility, and postpartum age were independent factors promoting reticulocytosis in newborns." (PMID 36419023, 2022). "From all sources searched (literature and pharmacovigilance databases), a total of 318 episodes of haemolytic anaemia associated with NF intake were reported, 42 in individuals who were confirmed as G6PD deficient or in whom G6PD deficiency was highly probable." (PMID 35529053, 2022). "G6PD gene mutations were detected in 18 of the 27 T1D patients with G6PD deficiency." (PMID 35313968, 2022). "Thus, a genotypic test is required to confirm the G6PD status in those suspected of having G6PD deficiency." (PMID 36339627, 2022). "Interestingly, the severity of G6PD deficiency was positively correlated to the magnitude of insulin deficiency, thereby further confirming that normal G6PD activity is necessary to preserve β-cell function." (PMID 36431166, 2022). "However, the therapeutic use of primaquine and tafenoquine is restricted because these drugs can cause hemolysis in individuals with glucose-6-phosphate dehydrogenase (G6PD) deficiency." (PMID 36339627, 2022). "Available evidence shows that the WHO-recommended SLD primaquine dose added to effective schizonticides is safe and well-tolerated even in individuals with G6PD deficiency, and therefore, it can be safely used in the African population with the mildest G6PD A- variant." (PMID 35216617, 2022). "G6PD deficiency is an X-linked inherited disorder that largely affects hemizygous males and homozygous females, whereas heterozygous females present normal, intermediate or deficient G6PD activity due to random chromosome X inactivation." (PMID 36212142, 2022). "Importantly, four patients had dual diagnoses with glucose-6-phosphate dehydrogenase (G6PD) deficiency: X-linked SCID (IL2RG), C6 deficiency (C6), IPEX syndrome (FOXP3), DiGeorge syndrome (TBX1)." (PMID 35757720, 2022). "Similarly, patients who have received G6PD-deficient stem cells from unaware donors and subsequently found to be enzymopenic can be presumed to have developed an acquired form of G6PD deficiency." (PMID 36431166, 2022). "Therefore, red blood cells defend against oxidative stress depending on G6PD and are more vulnerable to G6PD deficiency than other cells." (PMID 36160421, 2022). "G6PD deficiency is caused by mutations in the G6PD gene on chromosome X. Genetically, males are either G6PD deficient or G6PD normal, while females can be homozygous with G6PD deficiency (mutations are present on both X chromosomes) or heterozygous (one X chromosome is affected) or G6PD normal." (PMID 36038921, 2022). "Furthermore, G6PD genotyping should be used in conjunction with hemolytic risk assessment in those suspected of having G6PD deficiency, particularly in female patients." (PMID 36339627, 2022).
G6PD deficiency (continued). "It has been speculated that the presence of a high number of reticulocytes in newborns interferes with the diagnosis of G6PD deficiency since reticulocytes contain higher amounts of G6PD enzyme than mature erythrocytes." (PMID 36419023, 2022). "Based on the G6PD activities and genotypes of the 555 analyzed infants, a simplified decision-analytic model was developed to compare the cost of five diagnostic strategies for G6PD deficiency." (PMID 36212124, 2022). "The bimodal and trimodal distribution patterns of G6PD activity values observed in this study population coincided with the characteristics of hemizygous G6PD deficiency and normal males and heterozygous and homozygous G6PD deficiency and homozygous normal females, respectively." (PMID 36419023, 2022). "The high incidence of G6PD deficiency may reflect an evolutionary adaptation to the widespread prevalence of malaria, as G6PD-deficient red blood cells (RBCs) are hostile to the malaria parasites that infect humans." (PMID 36231003, 2022). "Following the identification of G6PD as a candidate for CoCl2‐induced endothelial dysfunction, we identified known chemicals that may ameliorate G6PD deficiency for therapeutic purposes." (PMID 35666067, 2022). "Hospitalized patients with G6PD deficiency and COVID-19 pneumonia had lower PaO2/FiO2 ratio, longer duration of mechanical ventilation, and reduced hemoglobin level compared with those with normal G6PD." (PMID 35287717, 2022). "At the first visit prior malaria treatment, malaria patients with G6PD deficiency (n = 28), compared to malaria patients with normal G6PD activity levels (n = 209), exhibited a significant decrease in the haemoglobin levels (11.03 ± 2.51 g/dl vs. 12.65 ± 1.97 g/dl; p = 0.003)." (PMID 36038921, 2022). "In this study, phenotypic analysis of G6PD enzyme activity indicated that 3.6% (18/498) of the study participants had < 30% enzyme activity of the AMM, which is stated as G6PD deficiency; and 56 female patients had intermediate G6PD enzyme activity (30–80%) of AMM with heterozygous gene mutation." (PMID 36076204, 2022). "G6PD deficiency is caused by one or more mutations in the G6PD gene, located on the X chromosome." (PMID 36145477, 2022). "These could divide the G6PD deficiency (in hemizygous male and homozygous female), and partial G6PD deficiency (heterozygous female) in healthy people’s blood samples." (PMID 36248708, 2022). "As G6PD deficiency is prevalent in the study area, we speculate that this selectively high median serum ferritin in G6PD-deficient individuals might have been part of the traits evolved to offer survival advantages against endemic diseases, like malaria." (PMID 35103063, 2022). "The higher prevalence of G6PD deficiency observed among females compared to males in this study could be due to the less optimal performance of the G6PD biosensor, which merits further validation using spectrophotometric method." (PMID 36076204, 2022). "However, primaquine induces a dose-dependent acute hemolytic anemia (AHA) in individuals with glucose-6-phosphate dehydrogenase (G6PD) deficiency that has led to a limited use of the drug especially in Africa where the condition is common." (PMID 35216617, 2022). "However, since the models adjusted for STH species, it is also likely that differences in diet, glucose-6-phosphate dehydrogenase (G6PD deficiency—a genetic disorder which affects males more often) or HIV can play key roles in anaemia in boys." (PMID 36288048, 2022). "Therefore, it is reasonable to expect that simultaneous examination of G6PD activity and sequencing of the entire G6PD gene or exons will become the standard clinical practice for the diagnosis of G6PD deficiency in the near future." (PMID 36212124, 2022). "G6PD Mahidol is the main genotype accounting for nearly 90% of G6PD deficiency." (PMID 36962413, 2022).
G6PD deficiency (continued). "Although this study had no haematological data to support the clinical impact of anti-malarial drugs on patients with G6PD MahidolG487A and other mutations, these findings provided evidence for malaria infection-induced haemolysis in patients with G6PD deficiency." (PMID 36038921, 2022). "In the future, simultaneous examination of G6PD activity and sequencing of the entire G6PD gene or exons could become standard practice for the diagnosis of G6PD deficiency and those at risk of G6PD deficiency-associated complications." (PMID 36212124, 2022). "In two former studies on Sardinian patients with RVO and NA-AION, the frequency of G6PD deficiency was found to be significantly lower than expected, suggesting that G6PD-deficient subjects may have a decreased risk of developing RVO and NA-AION." (PMID 35743352, 2022). "In malaria-endemic geographies such as Brazil, G6PD deficiency has important clinical implications for the radical cure of P. vivax malaria with 8-aminoquinoline drugs, which can lead to adverse health outcomes among patients with low G6PD activity." (PMID 34383774, 2021). "Among 104 G6PD alleles including 73 alleles from hemizygous males, 27 alleles from heterozygous females, and 4 alleles from homozygous/compound heterozygous females with G6PD deficiency, G6PD Viangchan (871G > A) was the most common mutation and was detected in 48 chromosomes (46.2%)." (PMID 33628497, 2021). "Therefore, this study examined the proportion of G6PD deficiency and the distribution of G6PD genotypes among malaria-infected Rakhine and Chin national groups across the western part of Myanmar." (PMID 34108049, 2021). "The aim of this study was to develop a molecular diagnostic test to enable an accurate, reliable and high-throughput platform for detecting G6PD mutations, which can be used as a supplement to the screening of G6PD deficiency, especially in heterozygous females." (PMID 33879156, 2021). "Most studies on G6PD deficiency and PQ-associated hemolysis focused on the G6PD A- variant, a combination of the two single nucleotide changes G202A (rs1050828) and A376G (rs1050829), although other polymorphisms may play a role." (PMID 33897764, 2021). "The reduction of metHb by methylene blue is dependent upon the NADPH pathway generated by G6PD, and its use is not only ineffective in these patients with G6PD deficiency but may worsen hemolysis due to its oxidant potential." (PMID 34178542, 2021). "Glucose-6-Phosphate Dehydrogenase (G6PD) deficiency (OMIM #300908), which was first described by Carson (1970), is an X-linked, incomplete-dominant, genetic disease, with an estimated global prevalence of 4.9% that affects more than 500 million individuals worldwide." (PMID 34659341, 2021). "In G6PD, the Asn-Asp missense variant rs1050829 (allele A+), associated with G6PD deficiency and in high LD with malaria resistance variant rs1050828 (allele A−) and several other variants, shows ΠAHz of 68.8, placing it in the top 0.5% of all variants, both on the X chromosome and genome-wide." (PMID 33185667, 2021). "The STANDARD G6PD Test enables point-of-care testing for G6PD deficiency." (PMID 34543346, 2021). "In a recent study in Afghanistan of Pashtun patients (in whom the main G6PD variant is the “severe” Mediterranean variant), the prevalence of G6PD deficiency in men (i.e., hemizygotes) presenting with vivax malaria was 4 times lower than in the healthy population." (PMID 33891587, 2021). "A later study conducted in Algerian males with clinical manifestations associated with G6PD deficiency (favism, neonatal jaundice, acute hemolytic anemia) demonstrated that 23% (23/100) were due to the Mediterranean-type G6PD genotype, while 46% had the African-type A- genotype." (PMID 34451395, 2021).
G6PD deficiency (continued). "G6PD deficiency has been associated to an increased susceptibility to Hepatitis A and E virus infections, while other studies demonstrated that G6PD-deficient cells supported enterovirus 71 replication more efficiently than control G6PD-expressing cells." (PMID 35071051, 2021). "In 808 cases of jaundice with normal G6PD, the admission level of total bilirubin was 300.30 ± 68.62 μmol/L, and the admission bilirubin level in 74 cases with G6PD deficiency was 334.43 ± 79.27 μmol/L, which was markedly higher than that of the former (P < 0.01)." (PMID 34895177, 2021). "The STANDARD G6PD Test is a promising tool to aid in POC detection of G6PD deficiency in Brazil." (PMID 34383774, 2021). "Indeed, a combination of both factors contributes to the severity of G6PD deficiency and, as a result, is an important determinant for classifying G6PD variants." (PMID 34934109, 2021). "Among healthy ethnic Karin women in Thailand heterozygous for the moderate Class III Mahidol variant of G6PD deficiency and having between 40% and 60% of normal G6PD activity, all three subjects receiving the 300mg single dose of tafenoquine hemolyzed approximately 8% of their red blood cells." (PMID 34270547, 2021). "At therapeutic hypnozoitocidal doses, primaquine invariably provokes a potentially life-threatening acute hemolytic anemia in patients having glucose-6-phosphate dehydrogenase (G6PD) deficiency, an X-linked trait affecting over 400 million people at a rate of about 8% where endemic malaria occurs." (PMID 34270547, 2021). "The purpose of this study was to explore the relationship between neonatal hyperbilirubinemia and G6PD deficiency and to investigate the effect of G6PD deficiency and UGT1A1 variant on bilirubin level of icteric neonates in Chaozhou, eastern Guangdong Province." (PMID 34895177, 2021). "Most individuals with G6PD deficiency are clinically asymptomatic, but some G6PD mutations could lead to mild and severe manifested phenotypes such as neonatal jaundice, acute or chronic hemolytic anemia, neonatal hyperbilirubinemia, and/or favism." (PMID 33536585, 2021). "Clearly, animal models of G6PD deficiency behave differently than they do in humans as for NO metabolism; in fact, although the Kitagawa model closely reflected a human G6PD mutation, blood pressure values were found to have decreased in the deficient animals compared to the controls." (PMID 34007401, 2021). "Thus, the G6PD activity should be screened when prescribing aspirin to patients with stroke, and the hemoglobin levels should be carefully monitored in those with G6PD deficiency." (PMID 34369077, 2021). "As such, drug-induced haemolysis associated with G6PD deficiency depends on two major factors: the first is the level of G6PD activity, which is determined by G6PD genotype, and the second is the exposure to oxidative stress, namely, metabolites of antimalarial drugs (8-aminoquinolines)." (PMID 33879156, 2021). "In China, newborn screening of G6PD deficiency is carried out by measuring G6PD enzyme activity." (PMID 34762759, 2021). "G6PD deficiency is an X-linked genetic disorder caused by a mutation(s) in the G6PD gene." (PMID 34934109, 2021). "Nevertheless, the HRM assays could be of great use for analysing G6PD mutations in supplement to phenotypic G6PD screening in heterozygous females as well as in populations suspected of having G6PD deficiency." (PMID 33879156, 2021). "However, dose-dependent hemolysis and methemoglobinemia are well recognized side effects, particularly in those with glucose-6-phosphate dehydrogenase (G6PD) deficiency." (PMID 34441049, 2021). "Glucose-6-phosphate dehydrogenase (G6PD) deficiency is the most prevalent inborn disorder." (PMID 32873296, 2020).